TNN (tenascin N)
Description:
Extracellular matrix protein that seems to be a ligand for ITGA8:ITGB1, ITGAV:ITGB1 and ITGA4:ITGB1 (By similarity). Involved in neurite outgrowth and cell migration in hippocampal explants (By similarity). During endochondral bone formation, inhibits proliferation and differentiation of proteoblasts mediated by canonical WNT signaling (By similarity). In tumors, stimulates angiogenesis by elongation, migration and sprouting of endothelial cells. Expressed in most mammary tumors, may facilitate tumorigenesis by supporting the migratory behavior of breast cancer cells.
Synonyms: TN-W; TNW
Tractability: Antibody: UniProt places it where antibodies can reach, with high confidence; UniProt predicts a signal peptide or a membrane-spanning region; its Gene Ontology location is reachable by antibodies, with medium confidence. PROTAC: ubiquitination databases record sites on it.
Gene: Protein-coding gene on chromosome 1 (175,067,509 to 175,148,075, forward strand). Ensembl gene ENSG00000120332.
Subcellular location: Secreted, extracellular space, extracellular matrix
Pathways (Reactome):
Extracellular matrix organization: ECM proteoglycans
Gene Ontology:
Molecular function: integrin binding; identical protein binding
Biological process: positive regulation of sprouting angiogenesis; regulation of cell adhesion; regulation of cell migration; cell-matrix adhesion; dendrite self-avoidance; negative regulation of neuron migration; neuron projection extension; osteoblast development; positive regulation of neuron projection development; regulation of bone development; regulation of multicellular organismal development; regulation of smooth muscle tissue development
Cellular component: extracellular matrix; tenascin complex; CA3 pyramidal cell dendrite; cell surface; hippocampal mossy fiber expansion; neuron projection; neuronal cell body
Genetic constraint (gnomAD): Loss-of-function variants: 114 observed, 122.31 expected, observed/expected ratio (o/e) 0.93, 90% interval 0.8 to 1.09. The upper end of that interval is the gene's LOEUF score, 1.09, which puts it in group 4 of 6, group 1 being the genes least tolerant of losing a copy. Missense variants: 1,648 observed, 1,631.7 expected, observed/expected ratio (o/e) 1.01, 90% interval 0.97 to 1.05. Synonymous variants: 678 observed, 650.66 expected, observed/expected ratio (o/e) 1.04, 90% interval 0.98 to 1.11.
Homologues: Orthologues: chimpanzee TNN (98% identical), macaque TNN (95% identical), pig TNN (87% identical), dog TNN (82% identical), mouse Tnn (81% identical), rat Tnn (81% identical), guinea pig TNN (80% identical), rabbit TNN (78% identical), tropical clawed frog tnn (35% identical). Paralogues in human: TNC (35% identical), TNR (32% identical), TNXB (30% identical), FN1 (19% identical), FCN1 (10% identical), FCN2 (10% identical), FIBCD1 (10% identical), ANGPT1 (10% identical), FGL2 (9% identical), FGB (9% identical), ANGPT2 (9% identical), FCN3 (9% identical), and 13 more.
Diseases named in the same sentence as TNN in open-access papers:
TNN is named in the same sentence as 46 diseases in open-access papers, as found by Europe PMC text mining. Sharing a sentence is not in itself a finding about the gene and the disease. The quoted sentences say what the papers report.
breast cancer (13 papers, 2017 to 2024). A primary or metastatic malignant neoplasm involving the breast. "Five variants were in genes which have been reported to be associated with breast cancer risk in at least 50 manuscripts in PubMed (DST, CHEK2, FASN, TNN, and PMS2)." (PMID 38136396, 2023). "The KM analysis, along with the typical IHC staining of SLIT3, TNN, IGHD, and KRRB1, showed that the expression was significantly different between normal and breast cancer tissues and confirmed the prognostic effect of the TME risk signature." (PMID 36059555, 2022). "In cancer, TNN expression is strongly induced and for breast cancer a role in migration and metastasis has been proposed." (PMID 33552067, 2020). "Initially, univariate Cox regression analysis revealed that 12 genes were associated with the prognosis of breast cancer, followed by LASSO analysis to derive a prognostic signature composed of 8 genes, including CERCAM, EMP1, SDC1, PRKG1, XG, TNN, WLS, and PDLIM4." (PMID 38728370, 2024). "In vitro experiments show that tenascin-W/TNN promotes migration of several cell types, including breast cancer cells, osteoblasts, and endothelial cells." (PMID 33552067, 2020). "Six variants had no additional breast-cancer-affected carriers identified in the pedigrees they were originally found in (in genes KIF15, TMEM192, MUC5AC, TEP1, ZFX, and TNN)." (PMID 38136396, 2023). "We found that TNN was significantly over-expressed in kidney renal clear cell carcinoma (KIRC) (p = 0.024) and prostate cancer (p ≈0), but significantly under-expressed in liver (p = 0.003) and breast cancer (p = 0.003)." (PMID 30934003, 2019). "Interestingly, expression levels of TNN and TNXB were significantly lower in breast cancer tissues." (PMID 32817625, 2020). "Thus far, the relationship of TNN, TRBV7-4, and PCP2 with cancer has not been reported, and our results suggest that these genes, as core pyroptosis genes, have important associations with breast cancer development and the immune microenvironment." (PMID 36158689, 2022).
bladder cancer (2 papers, 2021).
prostate carcinoma (2 papers, 2019). A carcinoma that arises from epithelial cells of the prostate gland. "68% (49/72) of patients with KIRC and 84.6% (44/52) of patients with prostate cancer have the same trend of over-expressed TNN." (PMID 30934003, 2019).
adenoma (1 paper, 2024). A neoplasm arising from the epithelium. "Top over-represented EV proteins from the adenoma ZMTH3 were mainly related to immune response (ISG15, BST2, IFI44), while top under-represented proteins identified in the adenoma ZMTH3 EVs were associated with migratory and adhesion activity (MXRA8, TNN, SERPINB8), similar to the WCLs." (PMID 39462388, 2024).
alcohol dependence (1 paper, 2013). Physical and psychological dependence on alcohol. "Two nearby genes, KIAA0040 and TNN have been mapped to 1q25.1 and have been recently identified in genome-wide association analyses as being significantly related to alcohol dependence." (PMID 24829844, 2013). "The KIAA0040 gene is flanked by two genes TNN and TNR with a plausible role in alcohol dependence." (PMID 24829844, 2013).
cyst (1 paper, 2020). A sac-like closed membranous structure that may be empty or contain fluid or amorphous material. "In 3 month old TNN(-/-) mice both the dentin and enamel formation have increased and the enamel epithelium contains cyst-like structures." (PMID 33552067, 2020).
developmental delay (1 paper, 2024). "In family HOU1842 with reported 1st-degree cousin parents, the initial ES analysis demonstrated a molecular diagnosis of microcephaly, developmental delay (DD), and intellectual disability (ID) due to a homozygous pathogenic variant in TNN (HGNC:22942) in both siblings." (PMID 38622594, 2024).
diabetes (1 paper, 2021). "Differentially regulated genes not overlapping with ERCB data also reflected diabetes-associated changes, such as extracellular matrix (ANGPTL4, TNN, DPT, COL9A2) or gestational diabetes (LAT2, HP, CXCL10, CD86, CD68, REN, SLC2A3, VCAM1)." (PMID 33923831, 2021).
gastric cancer (1 paper, 2021). A primary or metastatic malignant neoplasm involving the stomach. "Somatic mutations of MUC16 and TNN correlated with better survival in gastric cancer." (PMID 34307129, 2021).
Insulin resistance (1 paper, 2019). Increased resistance towards insulin, that is, diminished effectiveness of insulin in reducing blood glucose levels. "The GDF10 and TNN are novel biomarkers for the development of insulin resistance." (PMID 30678306, 2019).
invasive breast carcinoma (1 paper, 2020). A carcinoma that infiltrates the breast parenchyma. "As a next step we compared the expression levels of tenascin genes (TNC, TNN, TNR, TNXB) in invasive breast cancer using GEPIA program." (PMID 32817625, 2020).
tumor (21 papers, 2012 to 2025). "TNN was the most frequently mutated gene across different cancer types, and its mutation frequency could act as an independent marker for tumor mutation burden (TMB) in multiple cancer types." (PMID 34552618, 2021). "By comparing expression levels of 16 genes between 779 BRCA samples and 100 paired normal breast tissues, 7 genes expression, such as C7orf63, C9orf103, IGJ, ZNF385B and TNN, was significantly lower in tumor tissues as compared with those in normal tissues." (PMID 35853971, 2022). "In prior study, TNN expression indicated angiogenesis function by commonly found adjacent to the blood vessel in tumor samples." (PMID 35106969, 2022). "On the other hand, a recent study found that TNN was highly expressed in tumor cells and TNN may possibly function as a tumor marker for anticancer therapies." (PMID 35106969, 2022). "Gene ontology analysis of these DEGs showed that in advanced stage tumours, pathways such as cell adhesion (VCAN), ECM receptor interaction (COL1A2, COL3A1, ITGA11, and TNN) and pathways in cancer (JUN, and MYC) getting deregulated." (PMID 31292488, 2019).
cancer (14 papers, 2012 to 2025). A tumor composed of atypical neoplastic, often pleomorphic cells that invade other tissues. "The clinical outcome of TNN mutation in different cancer types is conflicted, indicating the role of mutated TNN in cancer is context-based." (PMID 34552618, 2021). "Reports demonstrated high-frequently mutations in TNN and MUC16 had better prognosis and immunotherapy efficacy than patients with the low-frequently mutations or the wild-type genes in cancer patients." (PMID 40066453, 2025). "Earlier studies on tenascin-W/TNN have mostly focused on the in vitro function or tissue expression in cancer." (PMID 33552067, 2020). "Our results show that nsSNVs found in multiple cancer types are located within exomes of TNN, KIR2DL1, OR4K15, and ZNF99 genes." (PMID 30934003, 2019). "Patients with cancer with high expression of the PCP2 and TNN genes were probably sensitive to AS605204 and FK886 and resistant to XAV939." (PMID 36158689, 2022). "LAMA1, CHAD, ITGA8, and COL11A1 consistently showed hypermethylation in more than half of cancer types; on the contrary, TNN, SPP1, COL6A6, and TNR consistently showed hypomethylation in more than half of types of cancer." (PMID 36311789, 2022).
TNN also shares sentences with these, for which no sentence is quoted: glioma (4 papers); colon cancer (3); lung carcinoma (3); colorectal cancer (2); pancreatic cancer (2); adenocarcinoma (1); adenosquamous carcinoma (1); astrocytomas (1); biliary tract cancer (1); breast tumors (1); carcinomas of the gallbladder (1); cardiomyopathy (1); cholangiocarcinoma (1); Cholecystitis (1); cholelithiasis (1); connective tissue disorder (1); Ehlers-Danlos syndrome (1); gestational diabetes (1); glioblastoma (1); hepatobiliary tumor (1); Intellectual disability (1); kidney cancer (1); liver cancer (1); melanoma (1); microcephaly (1); mucinous carcinoma (1); Obesity (1); oligodendroglioma (1); osteoporosis (1); pancreatic adenocarcinoma (1).
A further 3 diseases each share a sentence with TNN in 1 paper.